CCL20 (C-C motif chemokine ligand 20)
Diseases named in the same sentence as CCL20 in open-access papers (continued):
Sharing a sentence is not in itself a finding about the gene and the disease.
COVID-19 (67 papers, 2020 to 2026). A disease caused by infection with severe acute respiratory syndrome coronavirus 2. "This study aimed to determine how serum vitamin D status and gene expression of VDR, DEFA1-3, and CCL20 associate with COVID-19 risk in a Lebanese cohort." (PMID 40904798, 2025). "This prospective observational study aimed to assess how serum 25(OH)D concentrations and nasopharyngeal expression of VDR, DEFA1-3, and CCL20 are associated with COVID-19 status in Lebanese participants tested between January and March 2024." (PMID 40904798, 2025). "Elevated CCL20 levels are associated with severe COVID-19 outcomes, including acute respiratory distress syndrome (ARDS) and multisystem inflammatory syndrome in children (MIS-C), indicating a pathogenic role." (PMID 40904798, 2025). "In our research, SELE and CCL20 have been identified as potential diagnostic biomarkers for COVID-19 in conjunction with pulmonary hypertension (PH)." (PMID 38653779, 2024). "Increased circulating CCL20 levels in blood as well as respiratory tract samples have been reported in severe COVID-19 patients and linked to ARDS, but the profound link to fatal COVID-19 observed here is less appreciated." (PMID 34957382, 2022). "A decreased abundance of a cluster of several leukocyte chemotactic factors (MCP-4, CXCL12, CCL11, CCL19, CCL25, and CCL20) was observed in the COVID-19 cases and associated with a decrease in the cytotoxic T-cell marker CD8A." (PMID 34710339, 2022). "Of note, we observed distinct top correlating miRNA for each severity group for all tested CC, including for example IL6 and CCL20, two cytokines strongly associated with COVID-19 severity in our data." (PMID 34957382, 2022). "Severity group-specific associations between miRNAs and COVID-19-associated CC (e.g., IL6, CCL20) or clinical hallmarks of COVID-19 (e.g., neutrophilia, hypoalbuminemia) separated patients with similar CC levels but different disease severity." (PMID 34957382, 2022). "Fenofibrate decreases the expression of other cytokines (IL17, CCL2, and CCL20) implicated in COVID-19 pathology." (PMID 34582497, 2021). "The AR regulates two chemotactic factors, the chemokine (C-X-C motif) ligand-1 (CXCL1) and chemokine (C-C motif) ligand-20 (CCL20), which are encoded by COVID-19-induced genes." (PMID 32600476, 2020). "Conversely, in silico perturbation of COVID-19 human blood cells using human-Geneformer model predicted that deletion of genes CXCL2, IFITM3, and CCL20 would revert the COVID-19 cells towards a normal state." (PMID 40106407, 2025). "Contrary to our findings, CCL20 was previously reported to be elevated in the lungs of COVID-19 patients." (PMID 39666439, 2025). "Many of these genes with the highest fold-change and lowest p-values are related to immune responses and inflammation, and some of them, such as CCL20 and miR-21, have previously been connected with COVID-19." (PMID 41227320, 2025). "Conversely, individuals at moderate to severe risk of OSA with concurrent COVID-19 showed reduced levels of serum IL-6, Eotaxin-1/CCL11, and salivary MIP-3α/CCL20 compared to those with mild OSA risk and concurrent COVID-19." (PMID 38476500, 2024). "There was a statistically significant difference in the expression of SELE and CCL20 between the pulmonary hypertension and control groups and between COVID-19 and control groups." (PMID 38653779, 2024). "Increased CCL20 expression is correlated with increased circulating CCL20 levels during the prolonged course of COVID-19 and with prolonged viral clearance." (PMID 38543303, 2024). "In this study, because of the significance of SELE and CCL20 in the pathogenesis of COVID-19 and PH, we chose them as drug prediction and molecular docking targets." (PMID 38653779, 2024). "In this research, SELE and CCL20 were found to be indicators of COVID-19 and PH co-pathogenesis by various bioinformatics analyse and machine learning algorithms." (PMID 38653779, 2024).
COVID-19 (continued). "All of the 6 intersected genes have been reported to associate with COVID-19, including FGFR3, TP63, CXCL2, CCL20, IL1B and CXCL8." (PMID 37497545, 2023). "Analyses of hospitalized severe COVID-19 patients in other studies have also identified IL-6, IL-10, CCL20, and miR-451a as key factors closely related to COVID-19 mortality." (PMID 38140218, 2023). "For example, severe COVID-19 was linked to changes in IL-13, IL6 and IL-1B, and multiple chemokines (e.g. CCL20, CCL27, CXCL10)." (PMID 36171541, 2022). "We found that fatal COVID-19 was associated with higher levels of IL6, IL10, IL22, CXCL10, CCL2, and CCL20 and lower levels of miR-495-3p, miR-451a, and miR-29b-3p." (PMID 34957382, 2022). "Increased serum levels of IL-6 and IL-8 have also been associated with disease severity in COVID-19 adult patients and enrichment of CCL20 has been observed in mechanically ventilated patients with COVID-19." (PMID 36279276, 2022). "COVID-19 patients had lower levels of most classical inflammatory cytokines (G-CSF, CCL20, IL-1β, IL-2, IL-6, IL-8, IL-15, TNF-α, TGF-β), but higher plasma concentrations of CXCL10, GM-CSF and CCL5, compared to non-COVID-19 patients." (PMID 33272291, 2020). "Given the similarities in the pathophysiology of SARS-CoV and SARS-CoV-2 infection, more research must be done to determine if CCL20 is upregulated in COVID-19 patients as well, thus contributing to a potential cytokine storm." (PMID 32752138, 2020). "This rise in serum CCL20 levels over time may be due in part to hypoxic signaling having a greater effect due to increased lung damage and ARDS linked to COVID-19 progression." (PMID 40867589, 2025). "However, for patients with moderate to severe risk for OSA with concurrent COVID-19, there is a decrease in serum IL-6, Eotaxin-1/CCL11, and salivary MIP-3α/CCL20." (PMID 38476500, 2024). "The immunological response of different cells may be regulated by SELE and CCL20, leading to an increase in the incidence of COVID-19 coupled PH." (PMID 38653779, 2024). "In COVID-19 non-survivor genes related to neutrophil chemotaxis and migration, including CXCL10, CCL20, CCL8, C3AR1, CCL2, VAV3 are significantly upregulated; increased neutrophil is a typical signature of COVID-19 and closely linked to fatality, as already reported by other studies." (PMID 37949875, 2023). "This resulted in a model including CCL20, IL6, IL10, and hsa-miR-451a, which was compared to a model with only CCL20 (the most statistically significantly associated factor with fatal COVID-19, adjusted p = 1.02 × 109)." (PMID 34957382, 2022). "In addition, chemokine (C-C motif) ligand 20 (CCL20) has been reported as one of the most significantly elevated biomarkers in patients with severe COVID-19 in the intensive care unit." (PMID 35634344, 2022). "Indeed, the expressions of CCR6 and its sole ligand, CCL20, were both enriched in the lungs of mechanically ventilated COVID-19 patients." (PMID 35992306, 2022). "Our study also revealed CCL20 as a key correlate of fatal COVID-19." (PMID 34957382, 2022). "We identified 230 LUAD/COVID-19 DEGs and constructed a risk score containing 7 genes (BTK, CCL20, FURIN, LDHA, TRPA1, ZIC5, and SDK1) that could classify LUAD patients into two risk groups." (PMID 35733175, 2022). "Of the proinflammatory cytokines, the following are of particular interest: CCL20, which has been associated with the first severe acute respiratory syndrome coronavirus (SARS-CoV), and IL-1B, CXCL1, CXCL2, and CXCL8, which are associated with COVID-19." (PMID 32752138, 2020). "Therefore, targeting the CCL20/CCR6 axis could represent a promising future potential therapeutic opportunity for patients with severe COVID-19 who often exhibit elevated levels of Th17 cells." (PMID 40867589, 2025).
COVID-19 (continued). "Indeed, elevated levels of CCR6+CD8+ T cells were observed in the BAL fluid in acute COVID-19, which might be due to the chemokine CCL20 being overproduced by alveolar macrophages and other cell types at the site of inflammation." (PMID 36146713, 2022). "Likewise, higher levels of CCL2, CCL7, CCL20, and CXCL10 were associated with lower blood lymphocyte count and higher inflammatory markers (CRP and ferritin), which are clinical markers of severe disease and poorer outcome in COVID-19." (PMID 33704068, 2021). "Also, we found 6 existing drugs against 4 potential anti-COVID-19 targets (CCL20, CSF3, CXCL1, CXCL10) that might have novel anti-COVID-19 indications." (PMID 34582497, 2021). "Among COVID-19 negatives, VDR correlated with CCL20 (r = 0.59, p < 0.01); among positives, VDR correlated with DEFA1-3 (r = 0.45, p < 0.05)." (PMID 40904798, 2025). "The top molecules in the COVID-19 T1 and T2 data set with the greatest alteration in methylation compared to healthy controls included hypomethylated MUC20, VAV3, CCL20, and mir21 and hypermethylated GIT2, IFNGR2, FCER1G, and OLR1." (PMID 41227320, 2025). "In a subset of 70 individuals stratified by COVID-19 status, we measured VDR, DEFA1-3, CCL20, and GAPDH expression by RT-qPCR." (PMID 40904798, 2025). "The main inflammatory cytokines and chemokines widely produced by patients with severe forms of COVID-19 are IL-6, IL-8, IL-1β, TNF-alpha, IFN-gamma, MIP1α and 1β, CCL2, CCL5, CCL20, CXCL1, CXCL2, CXCL8, CXCL10, and CXCL17." (PMID 39768136, 2024). "We identified a remarkably strong pro-inflammatory cytokine/chemokine profile with high levels for sCD163, CCL20, HGF, CHintinase3like1 and Pentraxin3 in serum which correlated with COVID-19 disease severity and overall outcome." (PMID 38839796, 2024). "The pathophysiology of COVID-19-complicated PH is also influenced by SELE and CCL20-mediated neutrophil proliferation." (PMID 38653779, 2024). "Alongside, we observed a high expression of cytokines (CCL3, CCL4, CCL5, CCL7, CCL18 and CCL20) in the CD4+ TCM, Classical monocytes and NK cells in the COVID-19 patients." (PMID 36532041, 2022). "While responses were not different between bamlanivimab- treated individuals and those who received placebo, CCL2, CCL19, CCL20, CXCL8 and CXCL10 were upregulated in samples from the nasopharyngeal cavity and the circulating blood of patients with COVID-19." (PMID 35303909, 2022). "Repeating the analysis to only include first samples, showed again increased levels of CXCL9 and CCL20 in severe disease, but also increased levels of CXCL10 and a downregulation of CCL17 in patients with severe COVID-19." (PMID 34957382, 2022). "In large airway tissues, genes related to the mucosal layer (MUC4, MUC5AC, MUC5B) as well as cytokine-mediated signaling pathway genes (CCL20, CXCL1, CXCL6, CXCL6, MMP1) and type I interferon genes (IFIT3, ISG15, STAT1, MX1) were upregulated in COVID-19." (PMID 35233546, 2022). "With regards to circulating chemokine levels, CCL3, CXCL9, CCL20, and CXCL1 were significantly upregulated in samples from individuals with severe COVID-19 when compared against mild and moderate cases." (PMID 34957382, 2022). "In contrary, some important cytokines in COVID-19 cytokine storm such as CXCL10, IL-6, CCL2, CCL20, IL-8 and S100A9 showed a trend of slightly lower levels in patients with asthma in all three COVID-19 severity groups." (PMID 34238349, 2021). "Our study also found 4 additional targets (CCL20, CSF3, CXCL1, CXCL10) with existing therapies that have yet to be trialed in the COVID-19 patient population." (PMID 34582497, 2021). "In individuals receiving COVID-19 mRNA vaccines, increased levels of innate cytokines and chemokines such as CXCL9, CXCL10, CXCL11, IFN-γ, and CCL20 have been identified in the peripheral blood of adults, with CCL20 and IFN-γ showing the strongest correlation with post-vaccination symptoms." (PMID 40733695, 2025).
COVID-19 (continued). "This FFL among CCL20, miR-1256 and PPARG may be a novel regulatory module in COVID-19 complicated with pulmonary hypertension." (PMID 38653779, 2024). "Using only 2 reference genes, we were able to isolate 12 shared TFs and 25 shared TF-miRNAs.by FFL tool, This FFL among CCL20, miR-1256 and PPARG may be a novel regulatory module in COVID-19 complicated with pulmonary hypertension." (PMID 38653779, 2024). "Moreover, by ssGSEA, natural killer T cells, activated dendritic cells, activated CD4 T cells, neutrophils, and plasmacytoid dendritic cells were correlated with COVID-19 and PH, with SELE and CCL20 showing the strongest correlation with dendritic cells." (PMID 38653779, 2024). "While some genes involved in monocyte and lymphocyte migration and function were expressed in the COVID-19(+) TV group (CCL13, CCL8, and CCL20), a greater number of these genes were expressed in the COVID-19(-) PU control group (CCL19, CCL18, CXCL13, CCL4, CCL5, CXCL9)." (PMID 37026002, 2023). "Higher levels of several of these proteins were inversely correlated with viral load, including the cytosolic RNA sensor RIG-I (gene symbol DDX58), chemokines (CCL20 and CCL25), and other proteins (Keratin 19 [KRT19], amphiregulin [AREG]) previously shown to be upregulated in COVID-19 patients." (PMID 36239699, 2022). "Analysis of an independent cohort of 108 patients from a different center (Cohort 2) demonstrated feasibility of CC/miRNA profiling in leftover hospital blood samples with similar severe disease CC and miRNA profiles, and revealed CCL20, IL6, IL10, and miR-451a as key correlates of fatal COVID-19." (PMID 34957382, 2022). "The analyses of these 7 gene expression levels between different clinical features suggested that BTK, SDK1, CCL20, LDHA, and ZIC5 may serve as effective biomarkers for screening and characterizing patients with LUAD/COVID-19 at different stages." (PMID 35733175, 2022). "We additionally found 4 potential targets (CCL20, CSF3, CXCL1, CXCL10) with 6 existing drugs that could be repurposed for the treatment of COVID-19." (PMID 34582497, 2021). "PIMS-TS children had significantly elevated levels of cytokines, IFNγ, IL-2, TNFα, IL-1α, IFNα, IFNβ, IL-6, IL-15, IL-17A, GM-CSF, IL-10, IL-33 and IL-Ra; elevated chemokines, CCL2, CCL19, CCL20 and CXCL10 and elevated VEGF, Granzyme B and PDL-1 in comparison to COVID-19, seropositive and controls." (PMID 33813138, 2021). "In our study, we first showed that despite similar respiratory severity, plasma concentrations of numerous cytokines characterizing the “cytokine storm” (i.e. IL-1β, IL-6, IL-8, IL-15, TNF-α, CCL2, CCL4, CCL19, CCL20, TGF-α) were lower in COVID-19 compared to non-COVID-19 patients." (PMID 33272291, 2020). "Serum levels of CCL20 were also found to be significantly higher in patients who died of COVID-19 compared to those that survived, indicating that CCL20 levels are an important negative predictor of survival in COVID-19." (PMID 40867589, 2025). "Also, patients with COVID-19 were characterized by increased secretion of proinflammatory cytokines CCL20/MIP3ɑ, IL-10, IL-15, IL-27 in non-survivors than in controls." (PMID 36758022, 2023). "The gene expression comparison according to the COVID-19 disease status showed that the normalized VDR, DEFA1–3 and CCL20 expression is significantly higher in the negative group than in the positive group (P<0.05)." (PMID 40904798, 2025). "Importantly, our meta-analysis identified 4 potential novel targets (CCL20, CSF3, CXCL1, CXCL10) associated with COVID-19 pathogenesis, targeted by 6 existing drugs that have not been studied in clinical trials for treatment of COVID-19 and could be repurposed." (PMID 34582497, 2021).
colorectal cancer (64 papers, 2011 to 2026). A primary or metastatic malignant neoplasm that affects the colon or rectum. "C-C motif ligand 20 (CCL20) performs chemotaxis for leukocytes, and is associated with cancer progression including migration and proliferation for colorectal cancer, as well as remodelling of the tumor microenvironment (TME)." (PMID 39167197, 2024). "On the other hand, in colorectal cancer, CCL20 secreted by TAMs is associated with the recruitment of Tregs." (PMID 37445941, 2023). "CCL-20 promotes colitis-associated colorectal cancer by recruiting CC-chemokine-receptor-6 (CCR-6)-expressing B cells and γδ T cells through chemotaxis." (PMID 34574641, 2021). "CCL20 recruits regulatory T (Treg) cells and is associated with chemoresistance in the setting of colorectal cancer." (PMID 34700376, 2021). "In colorectal cancer specimens, concomitant expression of IL‐8 and CCL20 correlates with E‐cadherin loss and with lymph node and liver metastasis." (PMID 28599100, 2017). "To assess for an association of CCL20 and its receptor CCR6 with colorectal cancer, we evaluated the expression of CCL20 and CCR6 in human tumors." (PMID 24866282, 2014). "One study in colorectal cancer has demonstrated that tumour associated macrophages secrete CCL20 and are responsible for the recruitment of CCR6+ regulatory T cells which enhance tumour development." (PMID 23469070, 2013). "CCL20 signaling through CCR6 caused increased production of CCL20 by colorectal cancer cell lines." (PMID 24866282, 2014). "Interestingly, a role for macrophages in promoting colorectal cancer has been noted by a recent paper where the effect appeared to be at least partially due to the loss of macrophage-generated CCL20." (PMID 24866282, 2014). "Included within the upregulated genes in the concurrent mutation group were some previously linked with colorectal cancer carcinogenesis, including NFKBIZ, CCL20, LCN2, PLOD2, MUC1, and MUC4." (PMID 40757636, 2025). "Recently, it has been reported that the CCL20/CCR6 axis is implicated in HCC progression, colorectal cancer and pancreatic cancer." (PMID 40115013, 2025). "In colorectal cancer, CCL20 has been shown to be dysregulated, with elevated levels observed in tumor tissues and associations with cancer progression and poor clinical outcomes." (PMID 40757636, 2025). "In colorectal cancer, high expression of CCL20 in cancer cells promotes the recruitment of Tregs, making tumors resistant to 5-FU treatment." (PMID 39985603, 2025). "For example, EN2 plays a key role in promoting colorectal cancer progression primarily through the regulation of the expression of CCL20, which in turn promotes the proliferation and migration of colorectal cancer cells." (PMID 40889210, 2025). "The metastasis of colorectal cancer has also been demonstrated to be promoted by F. nucleatum through miR-1322/CCL20 axis and M2 polarization, which indicating the importance of host-microbiome interactions." (PMID 38589501, 2024). "Chemokines, including CXCL10, CXCL12, CX3CL1, CCL2, CCL5, CCL18, and CCL20, induce chemotaxis to promote cell migration and invasion in ovarian, lung, breast, and colorectal cancers." (PMID 38438872, 2024). "It has been shown that 5-FU therapy increased the expression of chemokine (CCL20) in colorectal carcinoma cells (CRC) in vivo by triggering FOXO1/CEBPB/NF-κB signaling, which aided in the migration of Tregs into TME." (PMID 38347575, 2024). "Fusobacterium nucleatum promotes colorectal cancer metastasis through miR-1322/CCL20 axis and M2 polarization." (PMID 37283793, 2023). "CCL20/CCR6 was shown to promote the growth of colorectal cancer through ERK phosphorylation in some studies." (PMID 36447119, 2023). "EN2 promotes the proliferation and invasion of colorectal cancer cells by regulating CCL20, thus promoting the progression of colorectal cancer." (PMID 36061185, 2022).